SNAI1 (snail family transcriptional repressor 1)
Diseases named in the same sentence as SNAI1 in open-access papers (continued):
Sharing a sentence is not in itself a finding about the gene and the disease.
lung carcinoma (113 papers, 2012 to 2025). "UDP-glucose, the substrate for NUDT22, has been linked to metastatic progression of lung cancer cells by directly interfering with translation of the EMT-promoting gene SNAI1." (PMID 36871087, 2023). "CAFs also deliver the transcription factor Snail homolog 1 (SNAI1) to lung cancer cells via exosomes and induce EMT through cadherin-1 encoding epithelial-cadherin and vimentin (VIM) encoding waveform proteins." (PMID 37122754, 2023). "Cancer-associated fibroblasts (CAFs) contain SNAI1, which is delivered to recipient lung cancer cells via exosomes of CAFs to promote EMT." (PMID 34511114, 2021). "Nuclear prothymosin α inhibits epithelial‐mesenchymal transition (EMT) in lung cancer by increasing Smad7 acetylation and competing with Smad2 for binding to SNAI1, TWIST1, and ZEB1 promoters." (PMID 40259641, 2025). "In this context, ACBD3 has minimal or moderate impact on cell proliferation but acts as a negative regulator of NOTCH signaling, resulting in reduced SNAI1 expression and impaired cell motility in mesenchymal lung cancer cells." (PMID 40189704, 2025). "Although studies on SNAI1 in lung cancer are limited, it has been shown that upregulation of miR-34a-5p and subsequent downregulation of SNAI1 induce apoptosis in lung cancer cells." (PMID 40028162, 2025). "We recently demonstrate that UDP-glucose 6-dehydrogenase (UGDH) enhances the stability of snail family transcriptional repressor 1 (SNAI1) mRNA to initiate the epithelial-mesenchymal transition, thus promoting the extravasation process of lung cancer cells." (PMID 41390768, 2025). "It has been reported that WNK1 affects the EMT of lung cancer cells through SNAI1 and enhances the mobility of lung cancer cells, which promoted us to examine the axis of ZYX/WNK1/SNAI1 in GC cells." (PMID 37692528, 2024). "TGF-β induced demethylation of H3K27Me3 in the SNAI1 promoter and overexpression of SNAI1 in lung cancer cells leading to EMT." (PMID 36674743, 2023). "Recent research suggests that miR-34a-5p plays a significant role in triggering apoptosis by suppressing SNAI1 in lung cancer cells treated with apigenin." (PMID 37168369, 2023). "SLIT2 is frequently inactivated in lung cancer, and knockdown of SLIT2 decreases the interaction between beta-catenin and E-cadherin/SNAI1 in lung cancer cells, resulting in increased cell migration and reduced cell adhesion." (PMID 35053460, 2022). "First, miRNA-30a inhibits the epithelial-to-mesenchymal transition by targeting SNAI1, and thus, its downregulation in lung cancer results in cancer invasion and metastasis." (PMID 34178448, 2021). "In this study, we found that apigenin induces apoptosis through down-regulation of SNAI1 by up-regulating miR-34a-5p in lung cancer cells." (PMID 33675467, 2021). "Phosphorylated uridine diphosphate-glucose 6-dehydrogenase (UGDH) interacts with HuR and mediates the interaction of HuR with SNAI1 mRNA, which enhances the stability of SNAI1 mRNA and promotes lung cancer metastasis." (PMID 33425493, 2021). "CAFs deliver the transcription factor SNAI1 to lung cancer cells via exosomes, thereby inducing epithelial transformation via CDH1 encoding E-cadherin and VIM encoding Vimentin." (PMID 34193120, 2021). "Our data revealed that, among the classic EMT-associated transcription factors (SNAI1 and ZEB1/2), PHRF1 substantially regulates the expression of ZEB1/2 and is required for the initiation of the EMT process in lung cancer cells." (PMID 32730336, 2020). "In both H1299 (lung cancer) and HeLa (cervical cancer) cell lines, SNAI1 protein levels were significantly decreased when autophagy was induced by rapamycin or starvation in HBBS." (PMID 30736337, 2019). "We created a score combining the expression of CDKN1A, ITGA6, and SNAI1, which was an independent prognostic biomarker for lung cancer patients." (PMID 31506430, 2019).
lung carcinoma (continued). "We co-cultured lung cancer cells with SNAI1-transfected CAFs and showed that the interplay between stromal cells and tumor cells facilitates epithelial tumoral cell EMT." (PMID 29383119, 2017). "Knockdown of SNAI1 mitigated ACBD3 deficiency-induced cell migration and invasion and anoikis resistance in epithelial H441 cells, suggesting that ACBD3 suppresses lung cancer cell dissemination through inhibiting the NOTCH-SNAI1 axis." (PMID 40189704, 2025). "Exosomal SNAI1 is essential for triggering EMT in lung cancer cells." (PMID 40490663, 2025). "miR-34a-5p may play a significant role in initiating apoptosis by downregulating Snai1 in apigenin-treated lung cancer cells." (PMID 39896297, 2025). "We then investigated the impact of BC on EMT in lung cancer cells and found that the expression levels of Slug, N‐cadherin, Snai1 and ZEB1 were significantly elevated in BC‐overexpressing 95C, 95D, A549 or PC9 cells, whereas that of E‐cadherin was robustly reduced." (PMID 36650118, 2023). "In lung cancer cells treated with apigenin, miR-34a-5p may play an important role in inducing apoptosis through down-regulation of SNAI1." (PMID 36768914, 2023). "Cancer-associated fibroblasts (CAF) may also be involved in the induction of EMT, such as SNAI1 delivered to recipient lung cancer cells via exosomes from CAF to promote EMT." (PMID 37700835, 2023). "Phosphorylated UGDH interacts with HuR to weaken the UDP-glucose-mediated inhibition of HuR binding to SNAI1 mRNA, thereby enhancing the stability of SNAI1 mRNA, increasing the epithelial-mesenchymal transition of lung cancer cells, and the migration of tumour cells and lung cancer metastasis." (PMID 35664798, 2022). "A recent study has revealed that CAFs deliver SNAI1 exosomes to lung cancer cells to induce EMT." (PMID 34193120, 2021). "The level of SNAI1 in exosomes is critical for EMT induction in lung cancer cells." (PMID 34511114, 2021). "The level of SNAI1 in exosomes derived from cancer-related fibroblasts is associated with the level of SNAI1 in cancer-related fibroblasts, which is crucial for inducting EMT in lung cancer cells." (PMID 33343360, 2020). "Recently P38-GSK3β-Snail signaling pathway induces EndoMT via HMGB1; however, the role of Snai1 in lung cancer angiogensis is largely unknown." (PMID 30975732, 2019). "The expression of E-cadherin, a hallmark of the epithelial phenotype, was decreased, whereas the expression of vimentin, a typical marker of the mesenchymal phenotype, was increased when lung cancer cells were co-cultured with CAFs in which SNAI1 was upregulated." (PMID 29383119, 2017). "To examine ERBIN's effect on TGF‐β‐induced EMT, we analyzed breast and lung cancer patient cohorts and found that ERBIN positively correlates with the epithelial marker CDH1 (encoding E‐Cadherin) and negatively correlates with the mesenchymal markers CDH2 (encoding N‐Cadherin) and SNAI1." (PMID 40859866, 2025). "SNAI1 has been reported in pancreatic, lung, and colon cancers and is involved in regulating the EMT process in pancreatic tumor cells; its high expression in lung cancer causes distant metastasis in lung cancer; and it has a role in inducing tumor stemness in colon cancer." (PMID 40295497, 2025). "While Lin and coworkers could induce erastin sensitivity by overexpression of TWIST or SNAI1 in primary mouse breast tumour cells, overexpression of SNAI1 in MCF7 breast or of TWIST in a lung cancer cell line did not change susceptibility to GPX4 inhibition." (PMID 34572111, 2021). "The levels of Snai1 in CAF-derived exosomes correlated with Snai1 expression in CAFs, highlighting its critical role in promoting EMT in lung cancer cells." (PMID 40244052, 2025).
lung carcinoma (continued). "Expression levels of NOTCHs and their target genes (SNAI1, SNAI2, HES2, HEY2) are positively correlated with EMT scores in LUAD, indicating activation of the NOTCH pathway in mesenchymal lung cancer cells." (PMID 40189704, 2025). "Previous studies have demonstrated that TCF4 can interact with TWIST1 to promote the expression of EMT-related genes, such as CDH2, VIM, SNAI1, and SNAI2, in embryonic stem and lung cancer cells." (PMID 35406121, 2022). "Targeting specific genes (such as SNAI1, ZEB1, miR-193A-3p, miR-210-3p, etc.)in these tumor-associated exosomes can effectively inhibit the exosome pathway to promote lung cancer metastasis, which may provide a new method for the prevention and treatment of lung cancer metastasis." (PMID 34511114, 2021). "Resveratrol was found to suppress the expression of EMT-inducing transcription factors such as SNAI1 and SLUG with concomitant increase in expression of E-cadherin along with suppression of vimentin and fibronectin in lung cancer cells." (PMID 31547193, 2019). "Interestingly, in lung cancer, RSF1-IT2 functions as a ceRNA to sponge miR-129-5p targeting SNAI1 and HMGB1, facilitating tumor metastasis and invasion." (PMID 34926441, 2021). "Transfecting CAFs with SNAI1 enhanced the modulatory effects of CAFs on lung cancer cell EMT when CAFs were co-cultured with A549 and H1299 cells, whereas transfecting CAFs with si-SNAI1 attenuated the modulatory effects of CAFs on lung cancer cell EMT." (PMID 29383119, 2017). "Furthermore, Vcl knockdown in 344SQ lung cancer cells selectively decreased Snai1 expression without affecting Zeb1, another mesenchymal marker." (PMID 40563579, 2025). "SNAI1, snail family transcriptional repressor 1, it is involved in regulating EMT processes in pancreatic tumor cells, SNAI1 is thought to induce tumor stemness and resistance to radiation in colon cancer and unstable expression of SNAI1 leads to distant metastasis in lung cancer." (PMID 38033866, 2023). "MTHFD2 was involved in lung cancer cell proliferation, migration, and apoptosis by mediating its downstream molecules, such as DNA helicases (MCM4 and MCM7), as well as ZEB1, Vimentin and SNAI1, which contributed to tumor cell growth and epithelial-to-mesenchymal transition (EMT) process." (PMID 35790743, 2022). "Moreover, this miRNA was also found able to reduce the GSK3β expression, always in lung cancer stem cells, as well as of activating the Wnt signaling pathway in gastric cancer cells through the induction of epithelial-mesenchymal transition (EMT) and the expression of VIM, SNAI1 and ZEB1." (PMID 27275761, 2016).
melanoma (104 papers, 2005 to 2025). A malignant, usually aggressive tumor composed of atypical, neoplastic melanocytes. "On the contrary, we detected SNAI1 expression in melanoma-associated fibroblasts, as indicated by double tdTomato-PDGFRα positive staining." (PMID 37516803, 2023). "SNAI1 positive expression in melanoma-associated fibroblasts was further confirmed in the melanoma transgenic BRAFV600E/PtenloxP/tdTomato model." (PMID 37516803, 2023). "Although this study shows an association between PXDN, NTN4, GLIS3 and SNAI1 and melanoma invasion, their roles in melanoma are most likely multifaceted." (PMID 27172792, 2016). "For example, circ_0084043 was a candidate to upregulate SNAILl (Snail Family Transcriptional Repressor 1) by interacting with miR-153-3p, thereby promoting melanoma cells’ proliferation, invasion, and migration." (PMID 40869968, 2025). "Several markers can serve as indicators of melanoma phenotype changes, such as Snai1, N-cadherin, and Cldn1." (PMID 39796281, 2025). "We have found co-expression of LOXL3 and SNAI1 in the perinuclear area of all investigated subgroups, and we have also found NES and SNAI1 co-expression in melanoma cells." (PMID 39273022, 2024). "We found co-expression of LOXL3 and SNAI1 in the perinuclear area of all investigated subgroups and NES and SNAI1 co-expression in melanoma cells." (PMID 39273022, 2024). "SNAI1 is overexpressed in melanoma, hepatocellular carcinoma, head and neck squamous cell carcinoma, and endometrial cancers." (PMID 39273022, 2024). "We also investigated SNAI1 expression among dysplastic nevi and melanoma subgroups and revealed higher SNAI1 expression in BRAF+ and BRAF– melanoma samples than in dysplastic nevi and melanoma in situ." (PMID 39273022, 2024). "Our study, although limited because of the small size of our cohort, provides evidence that the expressions of the investigated markers LOXL3, NES, and SNAI1 change with the progression of melanoma." (PMID 39273022, 2024). "In animal models, it has been shown that Snai1 depletion blocks melanoma growth by interrupting cell proliferation and enhancing apoptosis." (PMID 39273022, 2024). "Upon reviewing the literature, it becomes apparent that certain markers, such as LOXL3, SNAI1, and NES, are associated with melanoma development." (PMID 39273022, 2024). "Another mechanism that reduces CYLD expression is BRAF-mediated ERK (MAPK) activation via the transcription factor SNAIL1 (SNAI1) in melanoma." (PMID 37387450, 2023). "We extended our analyses to additional oncogenic BRAF and BRAFwt/NRASwt melanoma syngeneic models and confirmed SNAI1 reactivation in the stroma of these tumours." (PMID 37516803, 2023). "This is confirmed in syngeneic melanoma models where we find SNAI1 expression in CAFs in subcutaneous tumours and in lung metastases." (PMID 37516803, 2023). "We also validated SNAI1 expression in PDGFRα+ cells by using PDGFRα-CreERT2-tdTomato reporter mice and confirmed that blocking SNAI1 expression in PDGFRα+ fibroblasts reduced melanoma growth." (PMID 37516803, 2023). "We also analysed TCGA (The Cancer Genome Atlas) data from different cancers and found a positive correlation between Snai1 and Fap expression in 28 tumour types including melanoma." (PMID 37516803, 2023). "We also observed SNAI1 reactivation in PDGFRα+-CAFs from melanoma lung metastases in Snail1ME-WT mice that was confirmed in BrafV600E/PtenloxP/tdTomato melanomas." (PMID 37516803, 2023). "Our analyses of an inducible BRAF-driven melanoma reporter model reveal that SNAI1 in melanoma is reactivated in the stroma, particularly in CAFs." (PMID 37516803, 2023). "This study found that the epithelial-to-mesenchymal transition (EMT) inducer SNAI1 was markedly reduced in Salmonella-treated melanoma cells, as revealed by immunoblotting." (PMID 34207850, 2021).
melanoma (continued). "circRNA_0084043 has a sponging activity for miR-153-3p, that functions as a melanoma tumor suppressor by targeting Snai1 transcription factor responsible for promoting melanoma cells proliferation and invasiveness." (PMID 34638331, 2021). "The expression of EMT factor SNAI1 in melanoma and other cancers correlates with tumor aggressiveness, as it positively regulates various protumor genes, including metastasis inducers." (PMID 34207850, 2021). "It is known that SNAI1 acts as a key player in melanoma metastasis, as it affects a variety of tumor cell functions, and consequently, its expression correlates with poor clinical outcomes." (PMID 34207850, 2021). "Since Salmonella treatment significantly reduced SNAI1 expression, we assessed its biological impact on melanoma cell migration." (PMID 34207850, 2021). "The same effect was observed in human melanoma cells after Salmonella treatment, showing a significant decrease in SNAI1 expression." (PMID 34207850, 2021). "The elevated expression of SNAI1 in melanoma changes the expression of genes with regulatory functions in epithelial-to-mesenchymal transition (EMT)." (PMID 34207850, 2021). "Our data suggest that Salmonella directly inhibited melanoma metastasis in both in vitro and in vivo models by suppressing the Akt/mTOR/SNAI1 signaling cascade." (PMID 34207850, 2021). "Using microarrays data we show that both SNAI1 (gene encoding SNAI/Snail) and VIM (gene encoding vimentin) expression levels exhibited positive correlation with TMSB4X expression in human melanoma patients." (PMID 31921836, 2019). "Expression of NFATc2, MITF, AXL, ZEB1, SNAI1 (encoding SNAIL), and CDH2 (N-Cadherin) was then evaluated at the mRNA level, by qPCR, in a larger panel of 30 melanoma cell lines." (PMID 30710146, 2019). "Decrease in EMT markers (E-cadherin, YKL-40, N-cadherin, SNAI1) were seen with simultaneously decline in melanoma cells (BRAF, NAMPT) and stem cells (CD133, ABCB5) markers." (PMID 31126298, 2019). "Furthermore, in a melanoma cell lines study, Loxl3-silenced cells showed a marked decrease in Snai1 compared to the control." (PMID 39273022, 2024). "SNAI1+ melanoma cells display enhanced production of TGF-β, thrombospondin-1 (TSP1), CCL2, and lipocalin 2 (LCN2), which may have additional immunosuppressive effects beyond Treg and DC regulation." (PMID 38426087, 2024). "Interestingly, Snail1-induced EMT in melanoma cells promoted resistance to immunotherapy based on intratumour injection of dendritic cells and we show here that SNAI1 expression correlates with worse clinical responses to anti-PD-1 in melanoma patients." (PMID 37516803, 2023). "Indeed, primary melanoma cells showed an upregulation of Mitf and Twist1 and a downregulation of Snai1 and Prrx1 levels upon Loxl3 silencing." (PMID 35267510, 2022). "Interestingly, though, Salmonella treatment overturned the enhanced Akt/mTOR activity and increased SNAI1 expression in Akt-transfected melanoma cells." (PMID 34207850, 2021). "Given that Salmonella influences gene expression in tumors by modulating Akt/mTOR and MAPK signaling, we examined the effect of Salmonella treatment on the expression of SNAI1 in a panel of melanoma cell lines, as SNAI1 was known to be regulated, in part, by Akt signaling." (PMID 34207850, 2021). "SNAI1+ melanoma tumors were unresponsive to immunotherapy, but targeting SNAI1 with siRNA or anti-TSP1 monoclonal antibody could inhibit tumor progression and induce systemic immune responses." (PMID 35582229, 2020). "In melanoma cells, miR-153-3p targeted SNAI1 to inhibit cell proliferation and invasion." (PMID 31903137, 2020). "Likewise, SNAI1 overexpression in murine B16 melanoma cells resulted in inhibition of CTL lysis activity, inhibition of DC maturation and expansion of suppressive Treg-like CD4+ Foxp3+ cells in a mechanism involving thrombospondin (TSP1) and TGF-β secretion." (PMID 35582229, 2020).